POLR1B (RNA polymerase I subunit B)
Description:
Catalytic core component of RNA polymerase I (Pol I), a DNA-dependent RNA polymerase which synthesizes ribosomal RNA precursors using the four ribonucleoside triphosphates as substrates. Transcribes 47S pre-rRNAs from multicopy rRNA gene clusters, giving rise to 5.8S, 18S and 28S ribosomal RNAs. Pol I-mediated transcription cycle proceeds through transcription initiation, transcription elongation and transcription termination stages. During transcription initiation, Pol I pre-initiation complex (PIC) is recruited by the selectivity factor 1 (SL1/TIF-IB) complex bound to the core promoter that precedes an rDNA repeat unit. The PIC assembly bends the promoter favoring the formation of the transcription bubble and promoter escape. Once the polymerase has escaped from the promoter it enters the elongation phase during which RNA is actively polymerized, based on complementarity with the template DNA strand. Highly processive, assembles in structures referred to as 'Miller trees' where many elongating Pol I complexes queue and transcribe the same rDNA coding regions. At terminator sequences downstream of the rDNA gene, PTRF interacts with Pol I and halts Pol I transcription leading to the release of the RNA transcript and polymerase from the DNA. Forms Pol I active center together with the largest subunit POLR1A/RPA1. Appends one nucleotide at a time to the 3' end of the nascent RNA, with POLR1A/RPA1 contributing a Mg(2+)-coordinating DxDGD motif, and POLR1B/RPA2 participating in the coordination of a second Mg(2+) ion and providing lysine residues believed to facilitate Watson-Crick base pairing between the incoming nucleotide and the template base. Typically, Mg(2+) ions direct a 5' nucleoside triphosphate to form a phosphodiester bond with the 3' hydroxyl of the preceding nucleotide of the nascent RNA, with the elimination of pyrophosphate. Has proofreading activity: Pauses and backtracks to allow the cleavage of a missincorporated nucleotide via POLR1H/RPA12. High Pol I processivity is associated with decreased transcription fidelity (By similarity).
Synonyms: RPA135; Rpo1-2; FLJ21921; FLJ10816; RPA2; A135; TCS4
Tractability: Small molecule: a structure with a bound ligand is known. PROTAC: ubiquitination databases record sites on it; its protein half-life has been measured.
Gene: Protein-coding gene on chromosome 2 (112,541,915 to 112,579,818, forward strand). Ensembl gene ENSG00000125630.
Subcellular location: Nucleus, nucleolus; Chromosome
Subcellular location (Human Protein Atlas): Nucleoli fibrillar center; Cytosol
Pathways (Reactome):
Gene expression (Transcription): B-WICH complex positively regulates rRNA expression; NoRC negatively regulates rRNA expression; RNA Polymerase I Promoter Escape; RNA Polymerase I Transcription Initiation; RNA Polymerase I Transcription Termination
Gene Ontology:
Molecular function: 5'-3' RNA polymerase activity; DNA-directed RNA polymerase activity; DNA/RNA hybrid binding; protein binding; zinc ion binding; DNA binding; ribonucleoside binding
Biological process: transcription elongation by RNA polymerase I; neural crest formation; nucleolar large rRNA transcription by RNA polymerase I; termination of RNA polymerase I transcription; transcription initiation at RNA polymerase I promoter; DNA-templated transcription
Cellular component: fibrillar center; RNA polymerase I complex; chromosome; nucleoplasm; nucleus; nucleolus
Genetic constraint (gnomAD): Loss-of-function variants: 27 observed, 102.5 expected, observed/expected ratio (o/e) 0.26, 90% interval 0.19 to 0.36. The upper end of that interval is the gene's LOEUF score, 0.36, which puts it in group 1 of 6, group 1 being the genes least tolerant of losing a copy. Missense variants: 945 observed, 1,438.5 expected, observed/expected ratio (o/e) 0.66, 90% interval 0.62 to 0.69. Synonymous variants: 468 observed, 508.61 expected, observed/expected ratio (o/e) 0.92, 90% interval 0.85 to 0.99.
Gene-disease validity (ClinGen):
ClinGen rates the evidence that POLR1B causes each of these diseases.
Treacher Collins syndrome 4 (autosomal dominant): Moderate.
Homologues: Orthologues: chimpanzee POLR1B (99% identical), macaque POLR1B (99% identical), pig POLR1B (94% identical), rabbit POLR1B (93% identical), guinea pig POLR1B (91% identical), rat Polr1b (91% identical), mouse Polr1b (90% identical), dog POLR1B (90% identical), tropical clawed frog polr1b (77% identical), zebrafish polr1b (76% identical), Drosophila melanogaster Polr1B (45% identical), Caenorhabditis elegans rpoa-2 (45% identical). Paralogues in human: POLR3B (30% identical), POLR2B (29% identical).
Diseases named in the same sentence as POLR1B in open-access papers:
POLR1B is named in the same sentence as 21 diseases in open-access papers, as found by Europe PMC text mining. Sharing a sentence is not in itself a finding about the gene and the disease. The quoted sentences say what the papers report.
Treacher-Collins syndrome (5 papers, 2021 to 2026). A congenital disorder of craniofacial development characterized by bilateral symmetrical oto-mandibular dysplasia without abnormalities of the extremities, and associated with several head and neck defects. "The identification of causative mutations in the TCOF1 gene (85% of the cases), but also in the RNA polymerase I (Pol I) subunits POLR1C, POLR1D and recently, POLR1B strongly suggests that perturbation of ribosome biogenesis is the underlying cause of Treacher Collins Syndrome." (PMID 35646927, 2022). "More specifically, mutations in POLR1A cause Acrofacial Dysostosis Cincinnati type (AFDCin), whereas mutations in POLR1B, POLR1C and POLR1D and the Pol I associated protein, TCOF1/TREACLE lead to Treacher Collins Syndrome (TCS)." (PMID 37639467, 2023). "Treacher Collins Syndrome (TCS) (or Franceschetti Syndrome in other words) is a rare congenital deformity with a strong genetic background—with four genes being responsible (TCOF1, POLR1D, POLR1C and POLR1B)." (PMID 40649114, 2025).
lung carcinoma (4 papers, 2020 to 2025). "Similarly, POLR1B knockdown induces lung cancer cell apoptosis, VPS72 knockdown inhibits the proliferation, invasion, and migration of hepatocellular carcinoma (HCC) cells, and UBTF silencing suppresses melanoma cell proliferation." (PMID 37444571, 2023). "Recently, a study reported that POLR1B is up-regulated in non-small cell lung cancer and may serve an important modulator of lung cancer cell proliferation." (PMID 33133141, 2020). "used the STRING database to show that NR4A1 expression correlates with RNA polymerase I subunit B (POLR1B) activity, and POLR1B is an important modulator of lung cancer cell proliferation." (PMID 40666103, 2025).
non-small cell lung carcinoma (3 papers, 2020 to 2021). A group of at least three distinct histological types of lung cancer, including non-small cell squamous cell carcinoma, adenocarcinoma, and large cell carcinoma. "POLR1B regulates RRP12 to promote proliferation of non-small-cell lung cancer." (PMID 34194496, 2021). "POLR1B is one of the largest subunits of Pol I complex and associated with clinical outcomes of multiple types of human cancer including non-small cell lung cancer, lymphoma, but not been identified in CRC yet." (PMID 33202381, 2020).
Cluster headache (1 paper, 2024). A type of headache characterized by repeated attacks of unilateral pain lasting 15 to 180 minutes and associated with local autonomic signs. "POLR1B, which encodes DNA-directed RNA polymerase I subunit RPA2, has been linked to Treacher Collins and may be involved in cluster headaches." (PMID 38645487, 2024).
prostate carcinoma (1 paper, 2023). A carcinoma that arises from epithelial cells of the prostate gland. "Biased towards African-specific drivers (63 versus 9 shared), many are novel to prostate cancer (18/63), including several putative therapeutic targets (CHD7, DPF3, POLR1B, SETD1B, UBTF, and VPS72)." (PMID 37444571, 2023).
cancer (3 papers, 2020 to 2023). A tumor composed of atypical neoplastic, often pleomorphic cells that invade other tissues. "The ZFAS1/DDX21/POLR1B signaling regulation axis may also be a new biomarker for targeted CRC treatment, where ZFAS1 knockdown dramatically reduced cancer cell properties and increase apoptosis." (PMID 34262080, 2021).
infection (1 paper, 2017). The state of being infected such as from the introduction of a foreign agent such as serum, vaccine, antigenic substance or organism. "Due to the attenuated infection, HSV-1 induced host shutoff, as measured by RNA levels of the housekeeping genes POLR1B, SDHA, TBP, and PPIA, which were reduced." (PMID 29089033, 2017).
tumor (1 paper, 2020). "Consistent with the results obtained from the CRC cells, significant high expression of POLR1B was observed in 20 pairs of CRC tissues and matched tumor-adjacent controls using qPCR and RT-PCR assay." (PMID 33202381, 2020). "Thereafter, we detected the expression of POLR1B, and assessed possibly correlation with LncRNA-ZFAS1 or DDX21 in this included relative large samples containing 157 paired of CRC tissues and matched tumor-adjacent control tissues by TMA and IHC assays." (PMID 33202381, 2020).
POLR1B also shares sentences with these, for which no sentence is quoted: acrofacial dysostosis Cincinnati type (1 paper); ankylosis (1); atherosclerosis (1); breast carcinoma (1); choanal atresia (1); colon cancer (1); colorectal cancer (1); gastric cancer (1); hepatocellular carcinoma (1); lymphoma (1); melanoma (1); Miller syndrome (1); pancreatic cancer (1).